IL22 (interleukin 22)
Diseases named in the same sentence as IL22 in open-access papers (continued):
Sharing a sentence is not in itself a finding about the gene and the disease.
infection (continued). "IL-17A and IL-22 are related to Th17 immune response, which is mainly involved in mucosal immunity and plays critical roles in resisting pathogen infection." (PMID 40718811, 2025). "While in WT mice most cytokines measured by ELISA were increased 24 h post SARS-CoV-2 P21 infection compared to mock WT animals, Il-1β–/– and Il-1r–/– mice only differed in levels of IL-22 at this early time point." (PMID 40016339, 2025). "Treating mice with IL-18 BP at days 2 and 3 post-CR infection inhibited ILC2s expansion, and treating Il22-/- mice with rIL-18 rescued ILC2s expansion, together providing direct evidence that IL-18 plays a key role in ILC2s expansion during infection." (PMID 40591723, 2025). "Further, Ptpn2∆IEC mice displayed lower IL-22, IL-6, IL-17A cytokine expression post mAIEC infection compared to Ptpn2fl/fl controls." (PMID 40955058, 2025). "Both Il22−/− and Il22+/+ mice showed elevated serum renin and corticosterone following infection; however, increases were greater in Il22−/− mice, and FT resulted in significantly lower levels compared to untreated mice." (PMID 41361166, 2025). "Upon infection with C. rodentium, AhrdCAIR/dCAIR mice cleared the bacteria faster than wildtype mice, made more IL-22 and exhibited lower inflammation indicated by fecal Lipocalin-2 (Lcn2) expression." (PMID 40502009, 2025). "In this study, RNA sequencing and single‐cell RNA sequencing (scRNA‐Seq) revealed that reduced secretion of interleukin‐22 (IL‐22) by intestinal Group 3 innate lymphoid cells (ILC3s) is a significant factor contributing to the onset of TPN‐related infections." (PMID 40236767, 2025). "There were differences in the mRNA transcription and protein expression levels of IL-17 and IL-22 between mice that died (7, 14, and 18 days old) and those that survived (21 days old) after infection." (PMID 40006939, 2025). "As with our studies, administration of IL-22 resolved intestinal damage after epithelial damage and pathogen infection." (PMID 40502773, 2025). "Transplantation of fecal microbiota from donors in the TPN group resulted in a reduced proportion of IL‐22+ ILC3s in the intestines of ABX mice, thereby increasing their susceptibility to intestinal barrier damage and infection." (PMID 40236767, 2025). "The secretion of IL-22 in colonic explant cultures from uninfected WT and Atg7ΔIEC mice was similar, confirming that the induction of IL-22 observed on day 8 post infection in Atg7ΔIEC mice is dependent on C. rodentium infection." (PMID 39971913, 2025). "In both the Em1m and Em3m groups, infection markedly increased IL-22 expression and concurrently up-regulated the immune checkpoint molecules CD155 and its receptor TIGIT, thereby establishing an immune-tolerant microenvironment." (PMID 41562076, 2025). "As the infection burden increases and C. rodentium colonises a large surface of the colonic mucosa, IL-22 production shifts from ILC3s to CD4+ T cells." (PMID 41361166, 2025). "Other pro-inflammatory factors like IRF5, IL-12B, IL-1RN, IL-22, IL-8, and IL-33 significantly increased at 48 hpi in weaned piglets compared to newborn piglets after infection." (PMID 40589734, 2025). "A previous study in a mouse model demonstrated the increase in IL-22+ILC3 in the lung during Sp infection." (PMID 41104672, 2025). "In line with Ly6G immunostaining, neutrophil abundance increased upon infection, with Il22−/− mice displaying significantly higher colonic neutrophil numbers than Il22+/+ mice at 9 dpi; FT did not impact this increase." (PMID 41361166, 2025). "We infected C57BL/6 Il22−/− mice with C. rodentium by oral gavage, infection of Il22+/+ mice was used as a control." (PMID 41361166, 2025). "Despite persistent C. rodentium-associated pathology and higher faecal burden in the early and peak infection phases, FT-treated Il22−/− mice cleared C. rodentium at rates comparable to Il22+/+ mice and progressively recovered from colonic damage." (PMID 41361166, 2025).
infection (continued). "To investigate this, we assessed haematopoietic and immune cell changes by performing complete blood counts (CBC) on Il22+/+ and Il22−/− mice before and after infection." (PMID 41361166, 2025). "IL-22 can also trigger the expression of chemokines in synergy with other cytokines, recruiting and activating immune cells to resist pathogen infection." (PMID 40006939, 2025). "Yet, compared to deletion of espF alone, deleting the 12 accessory effectors has a milder effect on infection outcomes as was illustrated by infection of Il22-/- mice." (PMID 40599135, 2025). "Other cytokines assayed had weak correlation with atRA due to distinctly different cytokine levels in either Asp (IL‐21, IL‐22) or MRSA (TNFα) infection." (PMID 40031928, 2025). "In conclusion, our study confirmed that L. murinus and its tryptophan catabolite, ICA, can facilitate the differentiation of IL‐22+ ILC3s, thereby protecting intestinal barriers and reducing TPN‐associated infection." (PMID 40236767, 2025). "The secretion of IL-22 is usually activated in the early stages of infection or tissue damage and continues throughout the recovery process." (PMID 40006939, 2025). "To further investigate the role of IL-18 in driving ILC2 expansion, we used Il22-/- mice, which show reduced IL-18 expression during CR infection." (PMID 40591723, 2025). "Th-17 differentiation is triggered by IL-6 and IL-23 and produces IL-17A, IL-17F, and IL-22 cytokines that further recruit innate immune cells to the site of infection." (PMID 40586608, 2025). "In support of this, IL-22 protects against LPS-induced pregnancy failure in mice, although, during infection with the intracellular bacteria Ureaplasma, IL-22 was found to increase the rate of preterm birth." (PMID 40303843, 2025). "Il22−/− mice displayed lower expression of Reg3b and Reg3g both at baseline and post-infection compared to Il22+/+ mice." (PMID 41361166, 2025). "IL-22 has been shown to control infections by inducing the complement system, resulting in enhanced bacterial phagocytosis through the modulation of complement C3 expression." (PMID 38557196, 2024). "IL-22 also promotes intestinal epithelial cell fucosylation through the induction of the fucosyltransferase Fut2 to protect from infection." (PMID 39253083, 2024). "IL-17 and IL-22 reached the maximum on the third day after infection in the lung, and on the second day after infection in the small intestine and colon, respectively." (PMID 38727214, 2024). "Because Il22−/− mice started to succumb to C. rodentium infection beginning at Day 12 of post-infection, we selected this time point to analyze the expression of antimicrobial genes that are under IL-22 modulation." (PMID 38557196, 2024). "The cytokine is essential for clearance of C. rodentium and disease amelioration as Il22−/− mice eventually succumb to the infection, despite a functional adaptive immune response." (PMID 38557196, 2024). "On day 6 post-infection, ILC3s from Sirt6ΔRorc mice produced more IL-22 than Sirt6fl/fl littermate controls." (PMID 39253083, 2024). "In infection models, the IL-23‒IL-22 axis has been shown to exert protective effects on various enteric pathogens." (PMID 39379604, 2024). "This activation induces intestinal ILC3 to produce a significant amount of IL-22, which helps maintain intestinal stability, inhibits inflammation, and prevents infection." (PMID 38384457, 2024). "Luminal content from the ceca of IL-18 treated Il22−/− mice contained greater amounts of Muc2 protein after infection, suggesting local goblet cells released more Muc2 in response to IL-18 treatment." (PMID 39428744, 2024). "Despite the similar pathogen burdens, Il22−/− mice displayed significantly less cecal goblet cell depletion than WT mice upon infection, suggesting less mucin secretion into the lumen." (PMID 39428744, 2024).
infection (continued). "Although the level of IL-22 in lung tissue decreased shortly after infection, gradually returning to baseline after virus clearance, the gene expression of IL-22 remained constant." (PMID 38216935, 2024). "For this reason, disruptions in the activity of IL-22 can lead to chronic inflammatory diseases, impaired wound healing, keloid scars, infections, and carcinogenesis." (PMID 39195286, 2024). "In a gut microbiota-independent manner, CR colonizes in GF Il22-/- and Rag1-/- animals, triggers colonic epithelial tissue damage and systemic dissemination of CR, and results in lethal infections." (PMID 39630719, 2024). "IL-22 plays a crucial role in protecting against infections by promoting the increased production of AMPs, thereby enhancing antibacterial competence." (PMID 39195286, 2024). "The decreased survival observed in IL-22−/− mice was accompanied by an elevated clinical score early in the infection, surpassing even that of the IL-23−/− mice." (PMID 39635124, 2024). "As expected, infection led to a modest, but significant thickening of the distal colonic mucus barrier in Il22−/− mice, whereas the mucus barrier in infected WT mice was significantly thicker than both uninfected WT mice and infected Il22−/− mice." (PMID 39428744, 2024). "During early life, ILC3s are the main source of interleukin (IL)−17A and IL-22, which are important for the migration of neutrophils during infection and for barrier tissue regeneration and maintenance, respectively, in the immature adaptive immune system." (PMID 39695888, 2024). "On day 5 after infection, fewer colonic ILC3s from Ire1αΔRorc mice produced IL-22 and IL-17A than did ILC3s from Ire1αfl/fl mice." (PMID 38722686, 2024). "Surprisingly, only the IL-22−/− group exhibited a consistent and increasing level of fungemia throughout the analysis period, starting from the first week of infection." (PMID 39635124, 2024). "We observed that the infection significantly induced the expression of Il22 and Il17a in ILC3s, particularly in the CCR6+ cell compartments." (PMID 39013884, 2024). "The protective role of IL-22 during infection varies depending on the context and the pathogen involved." (PMID 38557196, 2024). "IL-1β and IL-18, elevated in CC024 mice after infection, act on lymphoid cells and enhance the production of IL-22." (PMID 39178306, 2024). "Such defects in IL-36R-deficient mice are secondary to the reduced production of IL-23 and IL-6, two key IL-22 inducers in the early and late phases of infection, respectively." (PMID 38674118, 2024). "Under the bacterial pathogen infection, IL-22 induced diarrhoea and clears intestinal pathogens by upregulating epithelial claudin-2." (PMID 39497434, 2024). "Further, when exposed to enterotoxigenic escherichia coli (ETEC) K88 infection, IL-22 stimulated epithelial cells to release β-defensin 1, and it alleviated apoptosis induced by the infection." (PMID 39497434, 2024). "Further, analysis of cytokine production revealed similarly upregulated CD4+IL-17A+, CD4+IFNγ+, and CD4+IL-22+ T cells in the colons of RORγtK256R/K256R and WT mice after infection." (PMID 39504243, 2024). "Further infection led to Tr-ILC3s proliferation and robust production of IL-22, thus promoting mucosal defense." (PMID 38407132, 2024). "Only one Il22−/− mouse out of 11 infected survived to Day 25 of post-infection, while all infected WT mice survived." (PMID 38557196, 2024). "The IL-17A, IL-17F, and IL-22-producing type 3 ILCs were significantly higher in the ace2Δ after 14 days post-infection." (PMID 39475280, 2024). "On the contrary, the mRNA expression of Il-22 and Il-23, two cytokines that maintain the homeostasis of gut microbiota, was obviously downregulated post infection." (PMID 39182245, 2024).
infection (continued). "Flow cytometry analysis revealed that CD4+, CD8+, and γδ+ T cell subsets all contributed to both IL-17 and IL-22 production on day 3 after infection, and the inhibition of IL-10 significantly enhanced the production of these cytokines by all T cell subsets." (PMID 38973612, 2024). "Despite the wild type (WT) and the IL-23−/− mice presented the same survival rate, with the animals dying around 19 days until 23 days post infection (dpi), the IL-22−/− mice presented lower survival with all animals dead before 19 dpi." (PMID 39635124, 2024). "This inflammasome dependency was mediated through the cytokines, IL-18 and IL-22, as they were necessary for the infection-induced thickening of the b1 mucus layer in the distal colon." (PMID 39428744, 2024). "We were able to observe VACV infection of resident EpCAM+ γδ T cells, as previously, and a large population of IL-22-producing resident γδ T cells, but production of IL-22 by VACV-infected γδ T cells was minimal." (PMID 38543790, 2024). "These macrophages can regulate the effector functions of IL-22-producing CD4+ T cells during the late phase of infection." (PMID 39379604, 2024). "In summary, our findings provide crucial insights into the meticulous regulation of anticryptococcal immunity during R265 infection by the IL-22 cytokine, shedding light on its implications for the overall disease outcome." (PMID 39635124, 2024). "Employing a mouse infection model, we assess the survival of animals using gene knockout mice for the IL-23 and IL-22 cytokines." (PMID 39635124, 2024). "Nevertheless, only the IL-22 absence impaired eosinophils frequency in the lungs during all stages of the infection." (PMID 39635124, 2024). "Recent studies have shown that the host immune system will produce specific cytokines to rapidly inhibit STM infection, among which IL-22 is one of the most upregulated cytokines in the intestine." (PMID 39080852, 2024). "FcεR1γ expression in ILC3s promotes the host defense against local C. rodentium and systemic Candida albicans (C. albicans) infections by promoting IL-17A and IL-22 secretion." (PMID 39013884, 2024). "Key genes responsible for maintaining epithelial integrity and promoting recovery, such as those encoding claudin-2, e-cadherin, and β1-integrin, displayed reduced expression during infection in Il22−/− mice." (PMID 38557196, 2024). "infection is decisive for the airway-blood barrier homeostasis, our data indicate that possibly those functions are impaired in the IL-22−/− mice during R265 infection." (PMID 39635124, 2024). "Blocking IL-10 during vaccination enhanced the frequency of IFN-γ+, IL-17+, and IL-22+ T cell subsets at the site of infection, which are critical for protection against S. aureus." (PMID 38973612, 2024). "Although, the relative percentage of total leukocytes decreases through infection, the IL-22−/− mice kept a lesser pronounced drop in their frequencies over time." (PMID 39635124, 2024). "During respiratory infection caused by Streptococcus pneumoniae, IL22RA2(−/−) mice were more resistant to contagion, had increased IL-22 levels in lung tissues, and sustained longer survival upon infection than control mice." (PMID 39195286, 2024). "In the S. Tm group, infection caused significant increases in TNF-α, IL-10, IL-22, and IFN-γ levels by 150.6%, 105.4%, 49.8%, and 103.4%, respectively, compared to the uninfected controls." (PMID 39456424, 2024). "Casp1/11−/− mice also showed an infection-induced increase in IL-22, but at levels significantly lower than for WT infected mice." (PMID 39428744, 2024). "IL-22BP plays an essential role in controlling the biological activity of IL-22 in healthy individuals and during infection or chronic inflammatory diseases." (PMID 39195286, 2024). "In our experiment, the level of RegIIIγ in intestinal tissue reached a maximum on the third day after infection, while the level of IL-22 reached a maximum on the second day after infection." (PMID 38727214, 2024).
infection (continued). "Because of the disparity in fungal burden between the IL-22−/− and IL-23−/−, mainly in the primary site, the lungs, we evaluate the impact of the infection in the lung integrity, and on the cytokine microenvironment of both lungs and brain." (PMID 39635124, 2024). "P. aeruginosa is recognized for inducing neutrophilic inflammation in airway epithelial cells, which triggers increased chemokine synthesis, including IL-8, IL-17A or IL-22, consequently leading to neutrophil recruitment to infection sites." (PMID 38790988, 2024). "On the one hand, Th17 cells secrete IL-17, IL-22, and IL-23 to recruit neutrophils, leading to aggravated inflammation at the site of infection." (PMID 39592944, 2024). "In contrast, in the immunocompromised GF Il22-/- mice, we showed that CR infection leads to 100% mortality, coinciding with severe colonic barrier damage and systemic dissemination of CR." (PMID 39630719, 2024). "At 12 days of post-infection, Il22−/− mice began to succumb to the infection, whereas WT mice started to recover and cleared C. rodentium from the gut." (PMID 38557196, 2024). "By contrast, upregulation of the IL-22–inducible Reg3 lectin family of AMP genes by Cr infection was PCC-specific." (PMID 38600382, 2024). "ILC3s represent a major early source of IL-22 in infection, where the cytokine upregulates antimicrobial peptides and mucin production promoting intestinal barrier resistance." (PMID 37483638, 2023). "Tryptophan is is a metabolite of the gut microbiota, it act as ligands that can activate the AHR on ILCs to induce IL-22 secretion, driving the release of antimicrobial peptides (AMPs) and providing protection from infections by pathogens." (PMID 37304260, 2023). "IL-22 levels remained similar between the 2 strains until the 10th week of infection, while in the 12th week, the levels of this cytokine were significantly reduced in infected ST2−/− mice." (PMID 37373379, 2023). "Interleukin 22 (IL-22) directly acts on IECs and contributes to the intestinal immune response to pathogen infection and epithelial wound healing." (PMID 37168865, 2023). "rL. lactis treatment prior to infection with C. perfringens led to temporal and spatial changes in expression of IL-13, IL-17, IL-18, IL-22, IL-12p40 and IFN-γ to β-actin from week 1 onwards in all sites along the intestine." (PMID 38164397, 2023). "In contrast, T cells are the major source of IL-22 in chronic inflammation and/or late stages of infection, acting mostly in the epithelial cells located at the crypts and protecting these from invasion by the pathogenic bacterium Citrobacter rodentium." (PMID 37101209, 2023). "Innate lymphoid cells (ILCs) predominantly produce IL-22 during the early stages of infection through an IL-23-dependent pathway, whereas CD4+ T cells secrete IL-22 during the later stages of infection via an IL-6-dependent pathway." (PMID 37646028, 2023). "In a murine cytomegalovirus study, different immune cells, such as T and NK cells, produced IL-22 in response to the infection." (PMID 37403036, 2023). "During the infection of C. rodentium, large amounts of IL-22 produced by RORγt+ILC3 exert protective effects by encouraging intestinal epithelial cells to express antimicrobial proteins." (PMID 37122757, 2023). "Next, we assessed expansion of Krt5-immunoreactive BC as a function of damaged area in IL-22 LOF mice following PR8 infection." (PMID 37726288, 2023). "In the same infection of C. rodentium, IECs’ intrinsic expression of IKKα is shown to be critical for IL-22 production by Group 3 ILCs in the gut." (PMID 37318214, 2023). "While IL22 seems to activate the cascade in response to an infection, IL18 is indispensable for the PC response and homeostasis." (PMID 36573340, 2023). "We showed that Th22 cells and IL-22 decreased in recipients with active infection, parallel to a decrease in Th17 cells." (PMID 37403036, 2023).